LGR5 (leucine rich repeat containing G protein-coupled receptor 5)
Diseases named in the same sentence as LGR5 in open-access papers (continued):
Sharing a sentence is not in itself a finding about the gene and the disease.
tumor (continued). "However, genetic ablation of LGR5+ cells in mouse intestinal tumor organoids (tumoroids) by the administration of DT restricted primary tumor growth but did not result in tumor regression." (PMID 34095127, 2021). "In the PDTX model, administration of SR3029 obviously delayed tumor growth, concomitant with an increased protein level of AES and a decreased expression of Wnt target genes (Axin2, Fibronectin and LEF1), stemness marker genes (CD44 and LGR5) and Notch target genes (HES1 and HES2)." (PMID 33754069, 2021). "Moreover, engineered organoids monitored by intra-vital imaging uncovered that most disseminated cells when they leave the primary tumour and seed to the liver are Lgr5 negative [51•]." (PMID 33422950, 2021). "Notably, tumour growth resumed unabated following treatment withdrawal, underpinned by dynamic conversion of Lgr5− non-CSCs into Lgr5+ cells." (PMID 33673710, 2021). "Which differentiated/non-CSC Lgr5− subsets are mobilized to replenish primary tumour growth, when the Lgr5+ CSC pool is compromised, and whether these are the same cell subsets that exhibit metastatic competence remains to be seen." (PMID 33673710, 2021). "While the precise mechanisms for the low frequency of LGR5 expression in CAC remains undefined, the wider spectrum of tumor morphology in CAC may be associated with absence of a LGR5-expressing intestinal stem cell phenotype." (PMID 33541282, 2021). "Accordingly, previous findings show that, while LGR5+ tumor cells can be detected in tumors from all CRC subtypes independent of their cellular composition, up to a third of individual CRCs tumors may lack detectable LGR5 levels." (PMID 33806447, 2021). "To determine whether both Lgr5+ CSCs and Lgr5− cancer cells were able to enter the blood circulation, we drew blood from the portal vein of mice bearing metastatic CRC to analyze CTCs directly draining from the primary tumor using flow cytometry." (PMID 32169167, 2020). "We next analysed the mRNA expression levels in tumour and adjacent mucosa samples from 17 paired CRC patients, which also suggested a significantly positive correlation between GLI1 and the stemness markers DCLK1 and LGR5 with elevated expression of all three genes in tumour tissues." (PMID 32814764, 2020). "To examine whether DAMPs are essential for the anti-tumor immune response of Arf1 ablation, we first interfered with the action of ATP and HMGB1 in Lgr5/Arf1/Apc intestinal CSC mice by administering ARL61756 (ARL), oxATP, suramin, and the Toll-like receptor 4 (TLR4) inhibitor." (PMID 31924786, 2020). "Anti-LGR5-ADC therapy is also a logical combination with the newly approved Tecentriq-Abraxane combo, which enhances CD8+ T cell killing through inhibiting PD-L1, to heighten complete tumor regression along with durable responses in the deadly high-grade ER− LGR5high BC." (PMID 32522170, 2020). "In conclusion, this is the first study to identify a subpopulation of LGR5+ epithelial cells endowed with tumor stem-like cell properties and intermediate EMT phenotype in solid AM (LGR5+ AM-EpiSCs), which may play an important role in its pathogenesis and recurrence." (PMID 32382005, 2020). "However, neither Lgr5 expression nor intratumor FoxP3+ Tregs correlated with any clinicopathological characteristics, including tumor size, degree of differentiation and TNM classification." (PMID 31417548, 2019). "However, although selective targeting of Lgr5+ CSCs through genetic ablation is effective to treat tumor temporarily, the anti-tumor effects would be overcome by non-targeted cancer cells eventually." (PMID 31358061, 2019). "However, the Wnt pathway is not significantly increased in the Notch1+ signature, suggesting that Notch1+ tumour cells do not present higher Wnt activity than Notch1+ ISCs and in agreement with reduced Lgr5 expression in these cells." (PMID 30696875, 2019).
tumor (continued). "A single targeting of Lgr5+ cancer cells may not be able to eradicate cancers and prevent tumor recurrence sufficiently for some certain cancer types at a specific stage." (PMID 31358061, 2019). "However, the results are inconsistent regarding the oncogenic role of Lgr5 as in mice mammary stem cells, Lgr5 was not a necessary component for tumorigenesis (tumor initiation) and progression." (PMID 31814939, 2019). "qRT-PCR analysis of these three FACS sorted populations showed that Notch1-derived lineages (in blue) express intermediate levels of both Lgr5 and differentiation markers, such as lysozyme, between non-labelled cells (in red) and Notch1-expressing tumour cells (in green)." (PMID 30696875, 2019). "However, work on genetically engineered mouse models shows that ablation of Lgr5 stem cells within Apc-driven adenomas, is not sufficient to affect tumour burden." (PMID 29498662, 2018). "Importantly, LGR5 and LGR6, and their ligands RSPO1–4, are upregulated in several cancers, lending support to the idea that elevated Wnt signaling may be a driver of tumor formation." (PMID 29416699, 2018). "Upon ablation of LGR5+ cells from these organoids using the DTR system, tumours regressed but were not eradicated owing to the presence of proliferating LGR5− cells, which could reform LGR5+ CSCs." (PMID 29844449, 2018). "Here, immunostaining of Lgr5 was performed in 204 cases of CRC, and the results showed that Lgr5 expression in CRC tumors staged as pTNM I-IV was heterogeneous, but significantly higher at the infiltrating front than at the expanding front, or at the tumor epicenter." (PMID 30046385, 2018). "In this study, we explored whether or not LGR5 was involved in the tumor development and cell signal transduction in HCC." (PMID 28881613, 2017). "In addition, LGR5 protein expression remained high in LGR5+ cells and was not detectable in LGR5– cells within the tumor xenografts tissues as determined by immunohistochemical staining and western blot." (PMID 28880275, 2017). "Strikingly, in the absence of APC, LGR5+ cells can fuel tumor growth." (PMID 28559443, 2017). "This delayed differentiation fits in well with the observation that LGR5+ and KRT20+ tumor cells reside in complementary compartments rather than intermingled in the same area and may suggest that distinct tumor niches facilitate stem or differentiation states." (PMID 28468934, 2017). "Hence, combined with our results we conclude that Lgr5 stem cells do not become tumor-initiating cells of cutaneous SCCs from exogenous carcinogens." (PMID 27409834, 2016). "However, we have shown that DCLK1 and LGR5 do not mark in HCT-116/OxR chemoresistant cells with or without OXA treatment in mice in tumor sections by immunochemical evaluation in this study." (PMID 27668882, 2016). "However, Lgr5 overexpression was not correlated with tumor grade (OR = 0.75 95 % CI: 0.37–1.54; P = 0.433)." (PMID 26674601, 2015). "However, Lgr5 expression was not correlated with sex, age, tumor type, tumor location, tumor length or distant metastases." (PMID 24666414, 2014). "We might consider Lgr5+ cells in the niches of normal tissues as stem cells; however, Lgr5+ cells within a tumor mass do not necessarily serve as tumor stem cells." (PMID 24340024, 2013). "In addition, our villin-TLR4 mice develop duodenal adenomas with Lgr5+ tumor cells, even in the absence of a genotoxic agent, supporting the idea that TLR4 activates proliferation." (PMID 23691015, 2013). "To strengthen the hypothesis that the Lgr5+ cells restricted to the bases of tumor glands are essential for the distinct ISC marker expression patterns in the upper and lower regions, we examined a GA with relatively diffuse LGR5 distribution and a slight basal accentuation of LGR5 expression." (PMID 24340024, 2013).
tumor (continued). "The levels of ‘stemness’ associated genes, such as CD133, Sox2, Oct4, Lgr5, Bmi1, and C-myc, were significantly decreased in shRNA-Ascl2/HT-29 and shRNA-Ascl2/LS174T cells in vitro as well as in the corresponding tumor xenograft (CD133 was not performed in shRNA-Ascl2/LS174T cells)." (PMID 22384170, 2012). "In non-neoplastic stomach mucosa, Lgr5 cells are found predominantly in mucous neck region; during intestinal metaplasia, they localize at the crypt base; and in GC, Lgr5 cells are present at the luminal surface, tumour center and the invasion front." (PMID 23217022, 2012). "However the distribution of LGR5+ cells is not random and the tumour biological effect depends on their spatial distribution." (PMID 22530031, 2012). "Since LGR5 suppresses wnt signalling and reduces EMT, expression of LGR5 might be expected to be reduced during specific stages of colorectal carcinogenesis, particularly at the invasive front of the tumours." (PMID 21829496, 2011). "However, formal evidence that Lgr5 identifies colon CSCs is still lacking and awaits the generation of reliable antibodies that can be used to isolate Lgr5+ tumor cells." (PMID 21311095, 2010). "Moreover, LGR5 enhances the expression of transcription factors such as Snail, Slug, and Twist, via EMT, which are involved in suppressing epithelial characteristics and promoting a mesenchymal, invasive phenotype, increasing tumor migration and invasion ability of cancer cells." (PMID 39821694, 2025). "Moreover, one recent study using a mouse model of CRC finds that tumour dissemination and metastatic colonisation is largely a function of cells lacking Lgr5 expression; however, tumour cell proliferation at the primary and metastatic sites obligately required Lgr5 expression." (PMID 39169164, 2024). "Thus, the results of these publications suggest that LGR5- non-CSCs are able to transform into LGR5-expressing CSCs, highlighting the phenotypic plasticity of these cells that appears to be crucial for primary tumor growth and metastasis." (PMID 35892561, 2022). "Moreover, the fact that Lgr5− differentiated tumour cells must re-express Lgr5 in order to repopulate the CSC pool, following its depletion during treatment, or to colonize the distant site holds promise for ongoing efforts to develop LGR5 antibody-drug conjugates." (PMID 33673710, 2021). "Therefore, the Wnt-activated and Lgr5-positive cells represent a type of resistance that may be considered tumor persistent rather than tumor progressive while patients are being treated with HHIs." (PMID 34611482, 2021). "Interestingly, the depletion of Lgr5+ cells ceases tumor growth of CRC, yet tumor growth is restored by the spontaneous reappearance of Lgr5+ cells in a dedifferentiation event in the primary tumor but not in the metastatic liver site, suggesting the absence of a CSC-supportive niche in the liver." (PMID 31557977, 2019). "However, dermal CD26 expression is upregulated in the stroma of Lgr6 but not Lgr5 or Lrig1 tumours." (PMID 29807713, 2018). "Furthermore, the LGR5+ SiHa-LGR5 cells were capable of tumor formation at a dose of 10 cells, but the LGR5– SiHa-AcGFP cells could not." (PMID 28880275, 2017). "However, the effect of Lgr5 on tumor angiogenesis has not been examined." (PMID 28404940, 2017). "Nevertheless, our data does not rule out that LGR5− cells could contribute equally to tumor growth." (PMID 28468934, 2017). "In murine skin, targeted activation of the RAS/RAF/mitogen-activated protein kinase (MAPK) pathway, coupled with deletion of Tgfbr1 in LGR5+ve stem cells, promotes rapid development of cSCC, which, in the absence of wounding, may mimic the kinetics of tumour induction in vemurafenib-induced cSCC." (PMID 27558455, 2016).
tumor (continued). "A positive correlation between LGR-5 and β-catenin expression (both in cytoplasm and nucleus) has also been reported, but co-localization of both markers in the same histological sections of a tumour has not been performed so far, nor has it been studied in the early phases of carcinogenesis." (PMID 23374535, 2013). "Critically, differentiation to an Lgr5+GLUL+ zone 3 fate, which is not permissive to oncogenesis, needs to be reversed for WNT-mutant clones to progress to early tumours." (PMID 41261129, 2026). "The central venous, Lgr5+Ctnnb1ex3/WT;R26LSL-MYC mutants did not form tumours in the liver but eventually developed intestinal polyps." (PMID 41261129, 2026). "Second, by simultaneously engaging both LGR5 and EGFR, the antibody facilitates rapid endocytosis and degradation of EGFR in LGR5-positive tumor cells—a mechanism not observed in cetuximab." (PMID 41375018, 2025). "Lineage-tracing analyses revealed that clonogenic CSCs are concentrated at the tumor edge, indicating that tumor growth is driven by spatially defined microenvironmental cues rather than intrinsic CSC markers like LGR5." (PMID 41373619, 2025). "Across the cohort, we find negative correlations between LGR5 expression and serum AFP at the time of transplant and the tumour cell proliferative fraction by Ki67 staining." (PMID 39169164, 2024). "Unlike Lgr5, which is shared by normal and tumor stem cells, DCLK1 was shown to be able to distinguish between normal and tumor stem cells in the gut." (PMID 38254219, 2024). "After immunodepletion of TGF-β1, Tregs failed to promoted Lgr5 expression in tumor cells, which indicated that Treg-derived TGF-β1 was the main factor that induced Lgr5 expression." (PMID 31417548, 2019). "Instead, tumors are kept by proliferative LGR5 negative cells that continuously try to replenish the LGR5 positive CSC pool, resulting in rapid re-initiation of tumor growth upon treatment cessation." (PMID 31057717, 2019). "Patients whose tumors exhibited high β-catenin levels, but not high LGR5 levels, did not display significantly shorter RFS periods compared to patients with low levels of tumor β-catenin expression." (PMID 29471794, 2018). "Surprisingly, Lgr5+ ablation did not affect primary tumor growth in the colonic mucosa, whereas liver metastases substantially shrank, suggesting that the microenvironment may be relevant for the function or recruitment of Lgr5+ cells at liver metastatic sites." (PMID 28559443, 2017). "In summary, based both on the expression level of IKKα in skin-related cancers and on the impact of LGR5 on BCC tumorigenesis, we conclude that IKKα is not expressed in skin SCC but in the nucleus of skin BCC and skin related non-malignant diseases." (PMID 27049829, 2016). "In our chemocarcinogenesis experiments Lgr5 progeny was recruited to the IFE, but did not contribute to any significant extent to the ultimate tumor masses." (PMID 27409834, 2016). "Other studies have, however, highlighted the role of Lgr5-negative CRC cells in the initiation of metastasis, suggesting that the relationship between tumour subpopulations could be dynamic." (PMID 33144692, 2021). "Furthermore, two landmark studies support a critical role for LGR5 expression in promoting metastatic growth in CRC: in mouse models and human tumour xenografts of CRC, LGR5 is not required for the metastatic spread but obligatory for the outgrowth of tumours at metastatic sites." (PMID 40405910, 2025). "In parallel, recent studies have highlighted that these non-canonical LGR5-negative stem populations may also be the drivers of CRC dissemination, tumour budding, and relapse, and while they may account for a small population in primary tumours, they are strongly enriched in metastatic lesions." (PMID 38319359, 2024).
tumor (continued). "Similarly, we used R26-tdTomato ApccKO/cKO Lgr5-EGFP-CreERT2 mice 6 weeks after Apc inactivation to isolate tdTomato+Trop2+ and tdTomato+Trop2− tumor cells and additionally a tdTomato-negative cell fraction that presumably contained differentiated Apc WT small intestinal epithelial cells." (PMID 36077674, 2022).
cancer (515 papers, 2008 to 2026). A tumor composed of atypical neoplastic, often pleomorphic cells that invade other tissues. "Human genetic studies have shown that mutations in WNT pathway genes, including LGR5, occur frequently in colorectal and other cancers and are associated with worse clinical outcomes." (PMID 40427162, 2025). "Organoid models of murine and human colorectal and other cancers contain LGR5-expressing (LGR5+) stem-cell-like cells and can be used to investigate the underlying mechanisms of cancer development, progression, therapy vulnerability, and resistance." (PMID 40427162, 2025). "Dysregulated Wnt activation, often due to mutations, leads to strong Lgr5 expression in various cancers." (PMID 39239558, 2024). "Glycolysis in Lgr5 expressing cancer cells was reduced along with the loss of LYZ+ cells by Dkk2 knockout." (PMID 38659853, 2024). "Highly specific antibodies against the extracellular domain of LGR5 were developed as (i) a research tool to study LGR5 biology, (ii) for diagnostic use in multiple cancer types and (iii) as novel immunotherapeutics." (PMID 39169164, 2024). "This included the downmodulation of canonical markers associated with both healthy and cancer cell stemness, such as Lgr5 and Cd44." (PMID 38658753, 2024). "While mutated intestinal Lgr5-positive stem cells are an established origin of cancer, other sources exist." (PMID 39456736, 2024). "To analyze the consequence of the loss of LYZ+ cells by Dkk2 knockout in cancer stem cell niche formation, we enriched Lgr5 positive cells that consist of stem cells, stem cell niche cells and transit amplifying cells in the homeostatic condition." (PMID 38659853, 2024). "This study indicates that the metastasis inducer MACC1 acts not only as a cancer stem cell-associated marker, but also as a regulator of LGR5 expression and LGR5-mediated stem cell properties." (PMID 38339354, 2024). "Previous studies have shown that MEK inhibitors reduce cell proliferation but increase the expression of genes such as Ctnnb1, Axin2, and Lgr5, which are highly associated with cancer development." (PMID 38277448, 2024). "Altogether, in a 3D co‐culture type of murine liver LGR5+ cells and cancer‐associated fibroblasts, we have demonstrated robust effects of CAFs in the promotion of LGR5 marked liver TICs." (PMID 37578396, 2023). "According to the recent studies, β-catenin regulated Lgr5 expression, a G-protein-coupled receptor containing leucine-rich repeats, which is associated with elevated malignancy and unfavorable cancer prognosis." (PMID 38201587, 2023). "The possibility of EMT occurring in cancer cells due to the involvement of LGR5 and cancer-associated adipocytes needs to be reexamined by expression analysis in cultured cells." (PMID 35123536, 2022). "In the antrum, Lgr5+ basal stem cells and/or +4 stem cells can produce oncogenic mutations for cancer initiation in mice." (PMID 35743714, 2022). "Frequency of CD44+ cells and expression levels of Cd44 and other cancer stem cell markers Ascl2, Lgr5 and Smoc2 were markedly reduced in Mex3a-deficient tumors." (PMID 36276637, 2022). "LGR5 was initially identified as a Wnt target gene, and its expression is closely associated with dysregulation of the Wnt/β-catenin pathway in cancers." (PMID 35778589, 2022). "LGR5 is one of the Wnt target genes, and its overexpression has been associated with abnormally enhanced Wnt/β-catenin signaling in many types of cancers." (PMID 35778589, 2022). "Reduced SRSF1 expression was associated with a corresponding reduction in LGR5 suggesting that in human cancer, as in our mouse models, SRSF1 mediates stem cell function." (PMID 35589755, 2022). "High LGR5 expression in carcinoma cells was associated with low CA-125 levels (P = 0.041) and was negatively correlated with recurrence rate (P = 0.013)." (PMID 35778589, 2022).